GEN1 (GEN1 structure-specific endonuclease)
Diseases named in the same sentence as GEN1 in open-access papers:
GEN1 is named in the same sentence as 20 diseases in open-access papers, as found by Europe PMC text mining. Sharing a sentence is not in itself a finding about the gene and the disease. The quoted sentences say what the papers report.
breast carcinoma (4 papers, 2023 to 2025). "Based on its critical function in DNA repair and the maintenance of genomic stability through the resolution of Holliday junctions, we considered GEN1 to be a candidate breast cancer susceptibility gene." (PMID 40649769, 2025). "LOH is a signature for most cancer syndromes with homologous repair deficiency, so we also evaluated the loss of heterozygosity at the GEN1 locus in breast cancer tissues from five carriers of c.1929_1932delAAAG." (PMID 40649769, 2025). "We also conducted a loss of heterozygosity (LOH) analysis at the GEN1 locus in breast cancer tissues from five patients with the frameshift variant of GEN1." (PMID 40649769, 2025). "Somatic frameshift mutations in GEN1 have been identified in breast cancer cell lines and primary tumors." (PMID 40649769, 2025). "We identified two putative loss-of-function variants of GEN1 among 617 Polish breast cancer patients with HBC and 300 controls by exome sequencing." (PMID 40649769, 2025). "The GEN1 gene is implicated in DNA damage repair, as are several high- or moderate-risk breast cancer susceptibility genes, i.e., BRCA1, BRCA2, PALB2, CHEK2, ATM, and BRIP1." (PMID 40649769, 2025). "To investigate the possible association of GEN1 variants with breast cancer risk, we sequenced this gene in 617 Polish women with hereditary breast cancer (HBC) and 300 Polish cancer-free controls." (PMID 40649769, 2025). "We also analyzed the tumor DNA samples from breast cancer tissues of five carriers with a GEN1 p.Lys645Cysfs*29 small deletion for loss of heterozygosity at the GEN1 locus." (PMID 40649769, 2025). "GEN1 is implicated in DNA damage repair, as are several other breast cancer susceptibility genes, and is included in several comprehensive next-generation sequencing (NGS) testing panels." (PMID 40649769, 2025). "Recent studies have primarily focused on the role of GEN1 in breast cancer susceptibility and cancer aggressiveness." (PMID 38890669, 2024). "The wild-type GEN1 allele was retained in all five breast cancers of carriers of p.Lys645Cysfs*29." (PMID 40649769, 2025). "For all breast cancer tissues from deletion carriers, the ratios were similar to those of the controls heterozygous for the variant (all ratios > 0.43), suggesting that the wild-type GEN1 allele was retained in all cancers." (PMID 40649769, 2025). "In this study, we investigated the potential contribution of GEN1 to breast cancer susceptibility." (PMID 40649769, 2025). "Somatic truncating GEN1 mutations havebeen reported in breast cancers; therefore, it would indicate the fact that GEN1 maybe a predisposition gene in breast cancer." (PMID 40636894, 2023). "Therefore, we sought to ask if germline variants in GEN1 predispose to breast cancer in Poland." (PMID 40649769, 2025). "However, GEN1 truncating variants are uncommon, and further epidemiological and functional studies are needed to explore if GEN1 mutations may confer increased breast cancer risk." (PMID 40649769, 2025). "First, we screened the entire coding sequence of the GEN1 gene in 617 Polish patients with hereditary breast cancer and 300 Polish population controls by exome sequencing (discovery sequencing phase) to search for putative loss-of-function mutations (protein-truncating variants)." (PMID 40649769, 2025). "Our study and other studies suggest that GEN1 variants do not confer an elevated risk of breast cancer (and probably other cancers)." (PMID 40649769, 2025). "We then compared the clinical characteristics of the breast cancer patients with and without the GEN1 c.1929_1932delAAAG variant." (PMID 40649769, 2025). "We don’t observe significant differences in the allele frequencies between different regions of Poland, i.e., for BRCA1, PALB2, CHEK2, NBN, RECQL, and also for the GEN1 founder p.Lys645Cysfs*29 variant, neither in breast cancer cases nor in controls (for GEN1 data)." (PMID 40649769, 2025).
breast carcinoma (continued). "We conclude that GEN1 is unlikely to be a high or moderate-risk breast cancer susceptibility gene." (PMID 40649769, 2025).
colon cancer (4 papers, 2010 to 2024). "It has recently been reported that GEN1 is absent in ovarian and colon cancer cell lines, suggesting that GEN1 is required for maintaining genome stability in human cells." (PMID 20661466, 2010). "Results from the analysis with the non-cancer multi-tissue network and the colon cancer GWAS included the genes KMT2B, PTBP1 and GEN1 (p-values 2.0 × 10− 6, 3.0 × 10− 6 and 3.0 × 10− 6, respectively)." (PMID 39010058, 2024).
Bloom syndrome (3 papers, 2012 to 2022). Bloom syndrome (BSyn) is a rare chromosomal breakage syndrome characterized by a marked genetic instability associated with pre- and postnatal growth retardation, facial sun-sensitive telangiectatic erythema, increased susceptibility to infections, and predisposition to cancer. "As anticipated from the known in vitro resolvase activity of GEN1 and consistent with the effect of depleting GEN1 in Bloom’s syndrome cells, we observed a severe defect in HR of DSBs in GEN1 depleted cells." (PMID 23166748, 2012). "Again, the combined depletion rather than single depletion of MUS81/GEN1 or SLX1/GEN1 in Bloom’s Syndrome (BS) patient cells can break the intact replication fork, leading to improper chromosome segregation and S-phase arrest." (PMID 36077130, 2022). "Furthermore, a recent study suggests that MUS81, SLX4 and GEN1 can compensate for lack of the BLM helicase in human cells by resolving HJs in somatic Bloom's syndrome cells." (PMID 22927825, 2012). "However, a recent study showed that co-depletion of GEN1 and Mus81 or SLX4 in Bloom’s syndrome cells resulted in severe defects in chromosome condensation, presumably due to unresolved Holliday junctions, when all three Holliday junction dissolution/resolution pathways were compromised." (PMID 23166748, 2012).
Fanconi anemia (2 papers, 2015 to 2022). Fanconi anemia (FA) is a hereditary DNA repair disorder characterized by progressive pancytopenia with bone marrow failure, variable congenital malformations and predisposition to develop hematological or solid tumors. "Though the family was nonsyndromic, we identified a combination of rare variants in Fanconi anemia (FA) genes FANCP/SLX4 (compound heterozygote - rs137976282/rs79842542) and FANCA (rs61753269) and a rare homozygous variant in the Holliday junction resolvase GEN1 (rs16981869)." (PMID 26201965, 2015).
bladder cancer (1 paper, 2022). "Another report on 98 patients with bladder cancer showed that mutations in DNA repair genes (CHEK2, ERCC5, GEN1, MLH1, PALB2, RAD50, RAD51B and RECQL4) are associated with an unfavorable cancer prognosis and 22% of patients had a mutation." (PMID 35395863, 2022).
endometriosis (1 paper, 2026). The growth of functional endometrial tissue in anatomic sites outside the uterine body. "RNA interference (RNAi)-mediated GEN1 knockdown reduced proliferation in both groups, with a more pronounced effect in endometriosis-derived EEOs (49.7% vs. 39.5% reduction, p = 0.05)." (PMID 41977222, 2026). "GEN1 mRNA and protein expression were reduced in primary endometrial cells from endometriosis patients compared with controls (mRNA: 0.52 ± 0.14 vs. 1.00 ± 0.19, p = 0.05; immunofluorescence intensity: 0.54 ± 0.18 vs. 1.00 ± 0.22, p = 0.05)." (PMID 41977222, 2026). "Furthermore, GEN1 knockdown directly increased γH2AX intensity in both groups, with endometriosis-derived EEOs showing a greater absolute increase (Δ1.26 vs. Δ0.72)." (PMID 41977222, 2026).
Ewing sarcoma (1 paper, 2016). A small round cell tumor that lacks morphologic, immunohistochemical, and electron microscopic evidence of neuroectodermal differentiation. "Increased sensitivity to DNA damaging agents in Ewing sarcoma can be explained by defective DNA break repair and down regulation of DNA repair genes BRCA1, GEN1, and ATM." (PMID 27248664, 2016).
gestational diabetes (1 paper, 2025). Carbohydrate intolerance first diagnosed during pregnancy. "This aligns with studies indicating that altered MAPK/ERK signaling is involved in CAKUT formation, with alterations caused by gestational diabetes and Gen1 and Robo2, which affect urinary tract development." (PMID 40563451, 2025).
glioblastoma (1 paper, 2015). The most malignant astrocytic tumor (WHO grade IV). "PhosphoSitePlus lists two phosphorylation sites at residues T380 and T438 in GEN1 that were found in a T-cell leukemia and a glioblastoma cell line." (PMID 26682650, 2015).
leukemia (1 paper, 2015). A malignant (clonal) hematologic disorder, involving hematopoietic stem cells and characterized by the presence of primitive or atypical myeloid or lymphoid cells in the bone marrow and the blood. "Taken together, these results suggest that concomitant inheritance of rare variants in FANCA, FANCP/SLX4 and GEN1 on the specific genetic background of this familial case, could lead to increased genomic instability, hematopoietic dysfunction, and higher risk of childhood leukemia." (PMID 26201965, 2015).
ovarian carcinoma (1 paper, 2024). A malignant neoplasm originating from the surface ovarian epithelium. "We hypothesized the variants of GEN1 influenced allele-specific microRNA binding which affected GEN1 expression, ovarian cancer cell function and tumor microenvironment." (PMID 38890669, 2024). "In addition, the mechanism by which common variants of GEN1 contribute to the increased mortality risk in Chinese ovarian cancer patients remains to be elucidated." (PMID 38890669, 2024). "In our study, we found that GEN1 contributed to the immune-suppressive function in tumor microenvironment, suggesting its importance as a therapeutic target for ovarian cancer." (PMID 38890669, 2024). "To extend our investigation, we assessed GEN1 protein expression levels of cell lines and observed that ovarian cancer cell lines exhibited higher expression level compared with normal ovarian epithelial cell line." (PMID 38890669, 2024). "We also initiated a comprehensive search for the expression of GEN1 protein in ovarian cancer tissues from The Human Protein Atlas datasets." (PMID 38890669, 2024). "The results showed an increase in expression level of GEN1 in ovarian cancer tissues, compared with normal ovarian tissues (P < 0.001)." (PMID 38890669, 2024). "Our findings suggested that while we could hypothesize an elevated GEN1 protein expression in ovarian cancer patients, the data was insufficient for conclusive statements due to the limited number of samples." (PMID 38890669, 2024). "Additionally, we used transwell assay to explore the invasion and metastasis ability of ovarian cancer cells after GEN1 overexpression." (PMID 38890669, 2024). "Additionally, a significant difference in GEN1 mRNA expression was observed between ovarian cancer tissues and borderline tumor tissues or low malignant potential tumor tissues (P < 0.001)." (PMID 38890669, 2024). "So far, the role of GEN1 in the ovarian cancer remained unclear." (PMID 38890669, 2024). "Furthermore, we used Kaplan Meier plotter to analyze the relationship between the GEN1 mRNA expression levels and survival outcomes in ovarian cancer patients." (PMID 38890669, 2024). "Taken together, our findings suggested that GEN1 may promote ovarian cancer cell proliferation, invasion and migration by influencing the expression of immune inhibitory factors, thereby presumably elevating the proportion of PMN-MDSCs and constructing an immunosuppressive tumor microenvironment." (PMID 38890669, 2024). "Therefore, we speculated that GEN1 might promote the malignant phenotype of ovarian cancer cells by influencing the cellular immune process." (PMID 38890669, 2024).
parasitemia (1 paper, 2019). "As before, we observed no changes in Gen0 pRBC loss in immune mice compared to controls, while total parasitemia, and emergence of Gen1 pRBC was blocked, with PMR substantially reduced from 17.3±7.7 in non-immune mice to 0.78±0.29 in immune mice." (PMID 30811498, 2019).
sterility (1 paper, 2022). "Silencing GEN1 or its loss of function results in male-sterility and persistent double-stranded breaks." (PMID 35412622, 2022).
cancer (16 papers, 2010 to 2025). A tumor composed of atypical neoplastic, often pleomorphic cells that invade other tissues. "In the cases that a GEN1 variant is found using the comprehensive testing panel, the variant carriers will want to know to what extent they are at elevated cancer risk." (PMID 40649769, 2025). "One major consequence of Holliday junction resolution by SLX4 and GEN1 is cancer-causing loss of heterozygosity due to mitotic crossing over." (PMID 33750946, 2021). "However, there is currently a lack of epidemiological data that supports the association of germline variants in GEN1 with increased cancer risk." (PMID 40649769, 2025). "After excluding GEN1 from the analysis, the WGS data identified six individuals in the BRCA1/2 cohort with LoF PPVs in four dominant cancer-associated genes, in addition to their clinically diagnosed BRCA1/2 mutation." (PMID 26023681, 2015). "Although the association between GEN1 with cancer risk is not established, this gene is included in the testing panels (i.e., the Fulgent Full Comprehensive Cancer Panel; and the Invitae DNA Damage Repair Panel)." (PMID 40649769, 2025). "In neither of these approaches did we see evidence of cancer predisposition for carriers of a GEN1 variant." (PMID 40649769, 2025). "Since replication stress is a common feature of cancer, it is tempting to speculate that the unscheduled GEN1 activation in S-phase might explain, at least in part, the genomic instability of these cells." (PMID 28290553, 2017). "Interestingly, while LPS treatment increased the proliferation and expression of the GEN1, KRIT1, CENPF, CPLANE1, STYK1, and KHDRBS3 genes, it decreased the expression of the cancer associated LOC610994, Gpatch4, SLC7A1, ATP13A2, and TEX45 genes in tumor enteroids." (PMID 35884586, 2022). "Thus, GEN1 might join the number of genes involved in recombinational repair such as BRCA1, BRCA2, and FANCJ/BACH, mutation of which is associated with cancer." (PMID 20661466, 2010). "Our results suggest the possible roles of GEN1, KRIT1, CENPF, STYK1, and Sam68/KHDRBS3 in promoting cancer cell proliferation, and these findings may provide a potential therapeutic target to control mast cell malignancy." (PMID 35884586, 2022). "In this scenario, we found that cancer cell expansion was not stopped even at the highest dose, demonstrating that the events in gen1 and gen2 are crucial for the response to treatment." (PMID 24146610, 2013). "However, at the present time, no cancer/disease-associated mutations have been identified in the NES region of GEN1, so it is not presently clear whether GEN1 misregulation is a driver for disease development." (PMID 25209024, 2014).
tumor (4 papers, 2021 to 2025). "Even though LPS treatment failed to diminish the expression of genes involved in proliferation and malignancy such as GEN1, KRIT1, CENPF, STYK1, and Sam68/KHDRBS3, it did reduce the expression of numerous genes implicated in tumor growth." (PMID 35884586, 2022). "A crucial NF-κB regulator, Sam68 (KHDRBS3), was also observed to be elevated in LPS-treated tumor enteroids, along with the genes GEN1, KRIT1, CENPF, and STYK1." (PMID 35884586, 2022). "Notably, the mRNA expression level of GEN1 was also correlated with clinicopathologic characteristics such as tumor stage (P = 0.012) and tumor grade (P < 0.001)." (PMID 38890669, 2024). "It is also possible that LPS-induced enhanced proliferation in tumor enteroids was caused by the increased expression of genes involved in the cell cycle process such as centromere protein F (CENPF) and flap endonuclease GEN homolog 1 (GEN1) as well as a receptor protein tyrosine kinase (STYK1)." (PMID 35884586, 2022). "Overexpression of GEN1 aggregated EOC cell proliferation, invasion and migration presumably by influencing the expression immune inhibitory factors, thereby elevating the proportion of PMN-MDSCs and then constructing an immunosuppressive tumor microenvironment." (PMID 38890669, 2024). "Overexpression of GEN1 aggregated EOC cell proliferation, invasion and migration presumably by influencing the immune inhibitory factors, thereby presumably elevating the proportion of PMN-MDSCs and then constructing an immunosuppressive tumor microenvironment." (PMID 38890669, 2024).
GEN1 also shares sentences with these, for which no sentence is quoted: adenocarcinoma (1 paper); Hereditary breast cancer (1); infection (1); skin cutaneous melanoma (1); T-cell leukemia (1).